POMC (proopiomelanocortin)
Diseases named in the same sentence as POMC in open-access papers (continued):
Sharing a sentence is not in itself a finding about the gene and the disease.
cancer (141 papers, 2005 to 2026). A tumor composed of atypical neoplastic, often pleomorphic cells that invade other tissues. "Cinobufagin-induced local analgesic effect might be associated with increased activity of POMC/β-END/μ-OR pathway released from invaded CD3/4/8 lymphocytes in cancer tissues." (PMID 28002791, 2017). "As it is well known, cancer cells possess the ability to surpass these mechanisms of inflammation resolution and promote neurochemical events that persistently activate POMC neurons, resulting in neuroinflammation." (PMID 34832866, 2021). "Among the POMC-derived peptides, α-MSH has been delineated to participate in the anti-neoplastic mechanism of POMC gene therapy via inflammation inhibition, neovascularization blockade, and sensitizing cancer cells to hypoxia-induced apoptosis." (PMID 31968661, 2020). "In addition, cancer cachexia may be triggered through IL-1 and other pro-inflammatory cytokines that activate the POMC/CART pathways, leading to a significant anorexic effect." (PMID 32466362, 2020). "Conversely, the expression levels of LEPR, POMC, MC4R, and NEGR1 in two (GBM and PAAD), two (CHOL and LUSC), four (LUAD, LUSC, PCPG, and THCA), and two (CHOL and PCPG) types of cancer were higher than those of the corresponding normal tissues, respectively." (PMID 33299884, 2020). "Although it is known that peptides derived from proopiomelanocortin, including ACTH, regulate cancer cell proliferation, the effect of ACTH on opioid peptides in cancer development is currently unknown." (PMID 37509632, 2023). "As cancer drastically alters energy balance, influencing the activity of specific brain nuclei regulating metabolism and food intake (e.g., hypocretin, AgRP, POMC, CGRP neurons) represents a strategy to not only improve quality of life, but limit energy availability to the cancer." (PMID 31773065, 2019).
infection (58 papers, 2013 to 2025). The state of being infected such as from the introduction of a foreign agent such as serum, vaccine, antigenic substance or organism. "Following infection of POMC neurons with the AAV encoding hM4Di, restraint-exposed mice injected with CNO showed a 66 ± 6% decrease in plasma ACTH compared with mice injected with vehicle." (PMID 32206712, 2020). "Even though the present study was the first to investigate the role of hypothalamic NF-κB pathway and POMC in acute skeletal muscle wasting caused by infection, it did have some limitations." (PMID 27922103, 2016). "However, mCoV-A59 infection completely abolished the expression of pre-opiomelanocortin (POMC) in the hypothalamus, a transcript expressed by POMC neurons, which is involved in the control of the autonomic nervous system and integrative physiology." (PMID 34151773, 2021). "After infection with DREADD hM3Dq or hM4Di, food intake results were used as an indication of CNO-induced AgRP or POMC neuronal activity, which were similar to findings reported earlier." (PMID 31506541, 2019). "In this study, we mapped the whole-brain direct inputs to POMC neurons in the ARC and NTS using cell-type specific infection and retrograde spread of modified rabies virus." (PMID 25870542, 2015). "The current study did not directly measure neuronal activity of AgRP or POMC neurons after infection with the DREADD virus, which is a limitation of this investigation." (PMID 31506541, 2019). "However, the infection of POMC neurons or AgRP neurons in the ARC did not produce any transsynaptic labeling in the NTS." (PMID 25870542, 2015). "By contrast, MC1-R protein was induced almost immediately after infection of Mel1700 cells, but there was no appreciable impact on the already high baseline level of TRP-1; instead, there was a virus-induced increase in mRNA for MC1-R, POMC (the precursor of α-MSH), and xCT (gene name SLC7A11)." (PMID 24701351, 2014).
metabolic disorders (27 papers, 2015 to 2026). "Collectively, our findings identify the TRIM31/Nrf2 axis as a key molecular switch governing POMC+ neuronal loss, hypothalamic injury and consequent peripheral metabolic disorders triggered by long-term PM2.5 exposure." (PMID 41514067, 2026). "These developmental windows represent important periods of vulnerability during which perturbations in the perinatal environment may lead to abnormal POMC and AgRP neuron development, causing lifelong metabolic diseases." (PMID 35474338, 2022). "Genetic defects in POMC are linked to metabolic disorders in humans and animals." (PMID 32369484, 2020). "This study was designed to further investigate the effects of glycemic dysregulation during pregnancy on the development and function of the POMC system as a mechanism promoting vulnerability to the development of metabolic disorders in the offspring." (PMID 37396180, 2023). "Not surprisingly, in HFD-fed mice, lacking LPL on microglia, there was a further down-regulation of CD68, and worsened phagocytic capacity, ultimately associated with less POMC-expressing neurons and more vulnerability to HFD-induced metabolic disorders." (PMID 33826123, 2022). "This cellular stress alters and probably kills anorectic pro-opiomelanocortin (POMC) neurons, reducing leptin sensitivity in the hypothalamus, a crucial step in the pathogenesis of the metabolic disorder." (PMID 35892629, 2022). "In a study analyzing mice offspring of dams fed conjugated linoleic acids (CLAs) to induce metabolic disorders, the CpG sites −100 and −103 bp of the Sp1‐binding site were found to be crucial for POMC expression." (PMID 31660128, 2019). "Here, we investigated whether TRIM31 in POMC+ neurons mediates PM2.5-induced hypothalamic injury and peripheral metabolic disorders in mice subjected to 24-week PM2.5 exposure." (PMID 41514067, 2026).
psychiatric disorder (24 papers, 2012 to 2025). A disorder characterized by behavioral and/or psychological abnormalities, often accompanied by physical symptoms. "Obesity in itself is frequently associated with psychiatric disease and disruption of the POMC system may play a part in the psychiatric components, whether obesity is present or not." (PMID 37275429, 2023). "This could be a model linking POMC with neurological and psychiatric disease, some of which may be linked to skin disease." (PMID 37275429, 2023). "Therefore, POMC and COMT are both potential pharmacological targets for treating psychiatric disorders." (PMID 27917343, 2016).
genetic disorders (14 papers, 2017 to 2025). "Its use is limited to people who have been diagnosed with one of three specific rare genetic disorders caused by proopiomelanocortin (POMC), proprotein convertase subtilisin/kexin type 1 (PCSK1), or leptin receptor (LEPR) deficiency." (PMID 36297523, 2022).
cardiovascular disease (11 papers, 2014 to 2026). "Among these associated protein-coding genes, MMP1, CTSB, POMC, RETN, and IL6R are known to be associated with SCAD or other cardiovascular diseases." (PMID 35425820, 2022).
bacterial infection (4 papers, 2014 to 2025). "Therefore, the aim of our study was to estimate the impact of the severity of the disease and the type of bacterial infection in CF patients on the serum level of appetite-regulating hormones including leptin, ghrelin, NPY, ASP, POMC, KISS, PYY, and α-MSH." (PMID 37111072, 2023). "In addition, we found that neither the severity of the disease nor the type of bacterial infection affects the level of other tested hormones that regulate appetite (ghrelin, NPY, ASP, POMC, KISS, PYY, and α-MSH)." (PMID 37111072, 2023).
neurodegenerative disease (3 papers, 2017 to 2024). A disorder of the central nervous system characterized by gradual and progressive loss of neural tissue and neurologic function. "The association of POMC with neurodegenerative diseases has been established through research involving a specific AD animal model." (PMID 39273520, 2024).
POMC also shares sentences with these, for which no sentence is quoted: adrenal hyperplasia (138 papers); adrenal adenoma (108); infantile spasms (92); hypopituitarism (91); Hyponatremia (85); Hypokalemia (84); primary adrenal insufficiency (80); adrenal tumors (71); endocrine disorder (57); acromegaly (52); ectopic ACTH syndrome (47); Hyperkalemia (39); adrenocortical tumors (29); COVID-19 (29); insomnia (29); pancreatic neuroendocrine tumor (28); osteoporosis (27); hyperprolactinemia (26); primary aldosteronism (26); Central hypothyroidism (25); Epileptic spasm (25); primary pigmented nodular adrenocortical disease (25); adrenal crisis (24); adrenocortical carcinoma (24); medullary thyroid cancer (23); Hypsarrhythmia (22); hypogonadism (20); Hirsutism (19); pituitary carcinoma (19); pulmonary carcinoid tumor (18).
A further 618 diseases each share a sentence with POMC in 17 papers or fewer.